INS (insulin)
Diseases named in the same sentence as INS in open-access papers (continued):
Sharing a sentence is not in itself a finding about the gene and the disease.
Hyperglycemia (continued). "This allowed us to evaluate the full extent of metabolic remodeling caused by hyperglycemia without the variable of insulin-affected metabolic pathways in the T1DM heart." (PMID 35163316, 2022). "Reduced insulin signaling in these tissues may result in systemic insulin resistance and hyperglycemia secondary to the decrease in glucose uptake." (PMID 35453469, 2022). "At high concentrations of insulin (in normal glucose levels), 80% of xylose is able to pass through the cell membrane, but this transport is competitively inhibited by glucose in situations of hyperglycaemia." (PMID 35335311, 2022). "When the combined use of oral hypoglycemic agents is not effective or conjunctive, insulin or non-insulin injections should be used to control hyperglycemia and reduce the risk of diabetic complications." (PMID 35574009, 2022). "Absolute or relative lack of insulin caused by pancreatic β-cell dysfunction, insulin resistance, or both is the main reason for hyperglycemia." (PMID 35193549, 2022). "In addition, the patient displayed dysglycemia (fasting hypoglycemia and post-prandial hyperglycemia, with low levels of C-peptide and insulin)." (PMID 35663312, 2022). "Our study suggested that the observed inhibition of hyperglycemia and elevated serum insulin level following IPCs infusion could be going back to the pancreatic secretion of insulin from the regeneration of Langerhans islets." (PMID 36248064, 2022). "Thus, a deficit of insulin in the body results in hyperglycemia, raising the blood glucose level, which in turn leads to many metabolic and life-threatening complications, including cardiovascular, nephropathic, and neuropathic diseases, amongst others." (PMID 35203540, 2022). "This incretin effect phenomenon is responsible for the majority of insulin secretion from the pancreas, and also for the control of postprandial hyperglycemia after oral glucose and food intake compared to intravenous infusion of glucose avoiding the digestive tract." (PMID 36289848, 2022). "In a relatively large propensity score-matched cohort of patients, a modest but significantly greater reduction in triglycerides was seen with DFPF (80%) versus conservative treatment (72%), which included insulin only in cases of hyperglycemia; a result comparable to this study." (PMID 35492338, 2022). "Patients unable to eat, with need for arterial and central venous line and without therapy restriction, are randomized upon ICU admission to tight (80–110 mg/dl) or liberal glucose control (only initiating insulin when hyperglycemia >215 mg/dl, and then targeting 180–215 mg/dl)." (PMID 36123593, 2022). "Other factors such as hyperglycaemia, increased oxidative stress, chronic inflammation, impaired insulin signalling, dyslipidaemia, renal polyol formation and the accumulation of advanced glycation end-products can also significantly contribute to the onset and progression of kidney disease." (PMID 36499723, 2022). "At present, insulin is the first-line treatment for hyperglycemia due to DIP." (PMID 35585514, 2022). "The research indicated that dendritic cells could promote the presentation of autoantigen and activation of diabetogenic T cells, which plays vital roles in insulin secretion and regulation of hyperglycemia function." (PMID 35909518, 2022). "High levels of circulating free FA and impaired insulin activity promote hyperglycemia, not only by increased glucose production by the liver but also by reduced glucose uptake by muscle and adipose tissue, and also may contribute directly to NASH." (PMID 35879786, 2022). "In mice, C3G was found to improve hyperglycemia and insulin sensitivity." (PMID 35453434, 2022). "In addition, leptin resistance in obese patients leads to excessive energy intake and affects the secretion of insulin, thus forming a microenvironment of hyperglycemia at the maternal–fetal interface." (PMID 36615730, 2022).
Hyperglycemia (continued). "Interestingly, the present study indicated that ICS II effectively combats T2DM, as evidenced by reducing hyperglycemia, concurrently enhanced glucose tolerance, and insulin sensitivity in db/db mice." (PMID 36139776, 2022). "When this insulin surge begins to decline, hyperglycemia and overt T2DM are observed." (PMID 35203115, 2022). "We conclude that a duodenal dual-wavelength light-emitting diode photobiomodulation improves hyperglycemia and hepatic parameters through photobiomodulation-mediated change of serum insulin, insulin resistance, insulin expression in the pancreatic β-cells, and the gut microbiome." (PMID 36359885, 2022). "Preclinical studies also support the role of ACE2 in β-cell homeostasis; in high fat diet mice β-cell de-differentiation is characterized by reduction of ACE2; deletion of ACE2 in diabetic mice induces hyperglycemia, β-cell oxidative stress and decrease of insulin secretion." (PMID 35250853, 2022). "Hyperglycemia was defined as a blood glucose concentration ≥8.6 mmol/L on ≥2 measures >1 h apart or any >10 mmol/L; treatment consisted of a reduction in the glucose infusion rate or starting insulin therapy to maintain glycemia at 4–10 mmol/L." (PMID 36291477, 2022). "The observed decrease in growth rate in malathion-poisoned rats may be explained by the insecticide’s diabetic effect, which manifests through the loss of the endocrine function of pancreatic islets (impairment of insulin secretion) and hyperglycemia." (PMID 35453442, 2022). "Similarly, in db/db mice, drinking H2-water has been shown to decrease levels of plasma glucose, insulin, and triglyceride, the effect of which on hyperglycemia was similar to diet restriction." (PMID 35614185, 2022). "Nevertheless, the insulin dose required to prevent ketosis is much lower than the dose needed to avoid hyperglycemia, which raises the question of whether COVID-19 promotes insulinopenia." (PMID 35936183, 2022). "Neonatal Diabetes mellitus (NDM) is defined by the presence of severe hyperglycemia associated with insufficient or no circulating insulin, occurring mainly before 6 months of age and rarely between 6 months and 1 year." (PMID 35518939, 2022). "In addition, the degeneration of pancreatic islets as a result of oxidative stress negatively affects circulating insulin level and results in persistent hyperglycemia." (PMID 35444531, 2022). "Unfortunately, insulin levels were not quantified in these studies; thus, it is impossible to identify whether the phenotypes described were the result of hyperglycemia or the combination of hyperglycemia and insulin." (PMID 36497026, 2022). "However, glucocorticoids have the potential to exacerbate the pathophysiology of TBIR by worsening insulin sensitivity, which leads to hyperglycemia and muscle wasting." (PMID 36157458, 2022). "In addition, hyperglycemia is a response to inflammation and is followed by neuro-inflammation, and insulin has an anti-inflammatory effect." (PMID 36672007, 2022). "While capsaicin’s effect on energy expenditure is unknown, it appears to treat hyperglycemia by boosting plasma insulin levels." (PMID 35268815, 2022). "It has been shown that fasting until 12:00 results in increased postprandial hyperglycemia and impaired insulin responses after lunch and evening dinner in healthy and T2DM subjects, due to effects directly on clock genes and time-controlled genetic expression." (PMID 35215472, 2022). "However, in patients with marked hyperglycemia, short-term insulin therapy is often used to release from glucose toxicity." (PMID 35574023, 2022). "The duration of hyperglycemia, nutritional intake and insulin treatment should be considered modifying factors; in addition, several confounding factors should be considered: perinatal characteristics, morbidities of prematurity, episodes of hypoglycemia and socio-demographic characteristics." (PMID 36291477, 2022).
Hyperglycemia (continued). "Sometimes, infection occurrence could lead to hyperglycemia and repeated insulin injections in the T1DM subjects." (PMID 36572938, 2022). "The other important miRNA in pancreatic islets is miR7a, whose heightened expression in pancreatic islets leads to chronic hyperglycemia and compromised insulin secretion, which also promotes beta-cell failure by inhibiting beta-cell transcription factors expression." (PMID 36060972, 2022). "In T2DM, elevated levels of proinsulin and des-31,32 proinsulin relative to plasma insulin could reflect an increased release of immature insulin vesicles, for instance due to chronic beta cell stimulation and hyperglycaemia." (PMID 36242807, 2022). "In individuals with T2DM, there is a daily rhythm in insulin sensitivity, with decreasing insulin sensitivity and increasing hepatic glucose production across the night, which leads to a fasting/morning hyperglycemia." (PMID 36160856, 2022). "Similarly, zebrafish overfed with 120 mg of commercial dry food versus 20 mg for controls for a period of 8 weeks exhibited higher body weight and BMI, hyperglycemia, glucose intolerance and increased insulin production." (PMID 35628176, 2022). "Moreover, oxidative stress, poor glucose control and long-lasting hyperglycemia, as well as exogenous insulin administration play an important role in intrahepatic fat homeostasis." (PMID 36531463, 2022). "High cortisol levels led to low insulin sensitivity and can evoke hyperglycemia." (PMID 36231598, 2022). "Starvation triggers insulin resistance, hepatic gluconeogenesis, and hyperglycemia." (PMID 36420952, 2022). "Many cytokines and chemokines that are released during the acute phase response to SARS-CoV-2 infection could possibly damage pancreatic beta-cells and impair insulin sensitivity, but their relationship with stress hyperglycemia is still unknown." (PMID 36059840, 2022). "Moreover, our findings are in agreement with previous studies indicating TRF’s role in increasing insulin sensitivity by modulating peroxisome proliferator-activated receptors (PPAR) and regulating the insulin signaling pathway in hyperglycemia." (PMID 36362316, 2022). "In female mice, hyperglycemia (>10 mM) resulted in mildly elevated insulin secretion in βInsrKO relative to control mice for the initial 48 h, which was not sustained for the duration of the experiment, while glucagon levels declined similarly in both genotypes." (PMID 35136059, 2022). "As hyperglycemia may promote a pro-inflammatory environment, lowering glycemic levels with insulin treatment could have had a protective effect." (PMID 36419098, 2022). "Diabetic APP/PS1 mice with insulin-controlled hyperglycemia had only slight cognitive deficits." (PMID 35077394, 2022). "Cross‐ApEn was used to measure pattern reproducibility in the two hormones using glucagon as control mechanism (0.78 ± 0.03 vs. 0.76 ± 0.03, fasting vs. hyperglycemia) and using insulin as a control mechanism (0.78 ± 0.02 vs. 0.76 ± 0.03, fasting vs. hyperglycemia)." (PMID 35822422, 2022). "In support of these observations, another study which also utilised anti‐Ccl4 antibodies reported that Ccl4 inhibition improved insulin sensitivity and lipid profiles, delayed the progression of hyperglycaemia and reduced systemic inflammation in high‐fat diet‐fed mice." (PMID 36245259, 2022). "In the treatment of hyperglycemia, polyphenols could act through insulin-dependent and insulin-independent mechanisms." (PMID 36145302, 2022). "Compared to a single hyperglycemia value, GDM pregnancies combined with fasting and post-load abnormal glucose levels (subtype 3) were associated with exaggerated disruptions in the glucose metabolic balance and insulin sensitivity." (PMID 36145103, 2022).
Hyperglycemia (continued). "Several studies have shown that curcumin improves insulin sensitivity, decreases hyperglycemia, improves insulin levels, reduces proinflammatory mediators such as interleukin (IL-6, IL-1β) and tumor necrosis factor-α (TNF-α) in diabetic patients, and increases their global antioxidant power." (PMID 36297570, 2022). "Moreover, osteocalcin (OCN), only secreted by insulin-activated osteoblasts and a marker of bone mineralization, is regulated negatively under hyperglycemia." (PMID 36297386, 2022). "In this scenario, hypoglycemia may occur following insulin administration for factitious hyperglycemia." (PMID 36171582, 2022). "For example, insome of them (Stockholm and Dallas colonies), the volume and density ofβ-cells are similar to those of the control; apparently, hyperglycemia iscaused by the defects in insulin secretion, while a decrease in the β-cellmass is observed in the Paris colony of GK rats." (PMID 36348712, 2022). "RRIs and SBP were acquired in control rats and the diabetic rats at the onset of hyperglycemia and insulin-treated euglycemia to determine HRV by the ratio of low-frequency to high-frequency power (LF/HF) and Poincaré plot as SSR (SD1/SD2), BRS, and MS-CXApEn." (PMID 35455136, 2022). "Research from the Mayo Clinic also suggested that subjects with genotype GA of rs3765467 exhibited a 100% increase in the total insulin secretion response to infused GLP-1 in the presence of hyperglycemia compared with subjects carrying the GG genotype." (PMID 36528605, 2022). "In agreement with this broader assignment, we have previously shown that L-DE-71- exposed female offspring show a combination of diabetogenic features including fasting hyperglycemia, insulin insensitivity, glucose intolerance and altered glucoregulatory hormones." (PMID 36277707, 2022). "Rapamycin-induced hyperglycemia could be controlled by insulin or dosage adjustment and returned to normal after rapamycin withdrawal, in this case, demonstrating that rapamycin-induced hyperglycemia was related to high-dose rapamycin." (PMID 35865311, 2022). "We then administered insulin over the same duration of time (4 weeks) to investigate whether prolonged insulin treatment reversed hyperglycemia-induced changes and to identify changes that were unresponsive to insulin treatment." (PMID 36552776, 2022). "It has been reported that PAS-related hyperglycemia originates from impaired insulin secretion." (PMID 35563608, 2022). "Inhibition of ER stress by the chemical chaperones 4-phenyl butyric acid (4-PBA) or taurine-conjugated ursodeoxycholic acid (TUDCA) restored systemic insulin sensitivity, enhanced the action of insulin on muscle, and normalized hyperglycemia in obese and diabetic mice." (PMID 35615361, 2022). "Dietary copper may promote poor glycemic control, while manganese could be protective against hyperglycemia and promote insulin sensitivity." (PMID 35789593, 2022). "Reducing acetate Ser473 phosphorylation may impair insulin signaling and reduce glucose uptake in peripheral tissues, leading to hyperglycemia in women with GDM." (PMID 36936475, 2022). "Additionally, first-degree relatives of diabetic patients and dysglycaemic subjects, probably due to insulin resistance, cannot compensate for postprandial hyperglycaemia normally." (PMID 35743370, 2022). "Untreated hyperthyroid patients (Graves’ disease) exhibited typical signs of β-cell dysfunction, namely the inability to adequately increase the insulin response to hyperglycemia, as well as an augmentation of proinsulin levels both in the fasting state and following a meal." (PMID 35740085, 2022). "T2DM subjects, who followed a 2-week TRF plan with a 9-h eating window per day demonstrated reductions in hyperglycemia and HbA1c, and increases in plasma insulin levels, even though there was no weight loss observed." (PMID 35215472, 2022).
Hyperglycemia (continued). "Therefore, our results suggest that adipogenesis in the bone marrow is insulin-independent and is enhanced by hyperglycemia and the availability of fatty acids." (PMID 36307522, 2022). "Taken together, these results indicate that on the early onset of T2D, Y1 receptor antagonism attenuates hyperglycemia, which can be attributed to improved insulin action as a consequence of reduced adiposity and/or directly due to the inhibition of the Y1 receptor in muscle." (PMID 34890851, 2022). "However, in our study, we used a model of type 1 diabetes, wherein hyperglycaemia is the result of a decreased insulin production after streptozotocin‐induced beta‐cell destruction." (PMID 35488737, 2022). "Additionally, maternal hyperglycemia due to low insulin sensitivity leads to a larger amount of glucose passing through the placenta to the fetus." (PMID 36558427, 2022). "Though insulin therapy in general effectively and safely maintains blood glucose levels close to normal in most individuals, its inability to closely mimic the endogenous pattern of insulin release leads to occasional hyperglycemia and related microvascular and cardiovascular complications." (PMID 36351917, 2022). "Finally, we confirmed that DNA‐delivered SWEETins (insulin‐expressing SWEET) can alleviate hyperglycemia in type‐1 diabetic (T1D) mice by producing insulin in response to xylose administration over a prolonged period of time." (PMID 36316222, 2022). "Thus, with prolonged hyperglycemia, the insulin+ cells were reduced, and instead, the glucagon+ cells increased." (PMID 35203411, 2022). "Insulin is frequently added to PN admixtures as a treatment for iatrogenic hyperglycemia." (PMID 35631667, 2022). "In response to hyperglycemia, pancreatic β-cells secrete insulin, which binds to its receptor, activates PI3/Akt signaling, induces the translocation of glucose transporter 4 to the plasma membrane, and promotes glucose uptake in various cells, such as skeletal muscle cells." (PMID 36145139, 2022). "A targeted skip of insulin before an exercise session can be a trigger for hyperglycemia." (PMID 36231598, 2022). "Alterations in glucose metabolism due to fluctuations in peripheral insulin resistance and endocrine interactions may result in stress hyperglycemia." (PMID 36079047, 2022). "Higher mean glucose levels in patients with SOFA ≥9 points are correlated with stress-induced hyperglycemia, and thus increased gluconeogenesis and insulin resistance, as well as with older patient age, which also translates into increased insulin resistance compared to younger groups." (PMID 35457586, 2022). "Insulin lowers glucose levels and limits the bad effects of hyperglycemia." (PMID 35629267, 2022). "Previous studies showed that a 30% increase in the insulin dose led to lower postprandial glycemia and did not cause a higher incidence of hypoglycemia episodes, but the frequency of hyperglycemia remained high." (PMID 35351180, 2022). "Information from in vitro and in vivo studies indicated that oxidative stress and hyperglycemia downregulated the expression of eNOS, whereas insulin and antioxidative supplementation could induce eNOS expression." (PMID 35966750, 2022). "Numerous experimental studies have shown that ADMSCs can improve pancreatic islet cell viability and function, ameliorate hyperglycemia, improve insulin sensitivity, restore liver function, counteract dyslipidemia, lower pro‐inflammatory cytokines, and reduce oxidative stress in the animal models." (PMID 34985174, 2022). "A mechanism for the INSTI-induced hyperglycemia was hypothesized to be due to the chelation of magnesium, thereby inhibiting the release and signaling of insulin." (PMID 36303801, 2022). "Serum insulin levels in mice 5 weeks after STZ administration almost decreased below the level of detection allowed by the sensitivity of the insulin assay, confirming that hyperglycemia was associated with a secretory deficiency of insulin." (PMID 35697861, 2022).